BARD1 (BRCA1 associated RING domain 1)
Diseases named in the same sentence as BARD1 in open-access papers (continued):
Sharing a sentence is not in itself a finding about the gene and the disease.
breast cancer (continued). "In this study, we generated new in-vivo treatment models of Brca1- and Bard1-mutant breast cancer that recapitulate the striking response to PARPi, acquired resistance, and recurrence that is observed in patients with breast cancer." (PMID 38956205, 2024). "Numerous human and mouse studies have looked at NF2-mutations in breast cancers and have found that these tumors indirectly modulate Hippo signaling when simultaneously mutated with BRCA1 and BARD1." (PMID 39796693, 2024). "Nonetheless, other genes in the HRR pathway, such as the RAD51c, PALB2, BRIP1, and BARD1 gene defects, have also been shown to impact breast cancer progression and outcomes." (PMID 38397152, 2024). "Using new PARPi-resistance models of Brca1- and Bard1-mutant breast cancer generated in-vivo, we identified FLT1 (VEGFR1) as a driver of resistance." (PMID 38956205, 2024). "According to the NCCN guidelines v2.2024 (27 September 2023), germline PVs in the genes ATM, BARD1, RAD51C, RAD51D, NF1, and CHEK2 confer an absolute breast cancer risk between 17% and 40%." (PMID 38893140, 2024). "Carriers of PALB2, BARD1, RAD51C, RAD51D, ATM, and CHEK2 are at higher risk of breast cancer as well." (PMID 37458761, 2023). "Exposure to tetrachlorodibenzo-p-dioxin (TCDD) increased the level of has_circ_0001098, which inhibited breast cancer development via the miR-3942-3p/BARD1 axis." (PMID 37243750, 2023). "Variants in key genes of HR, such as BRCA1, BRCA2, PALB2, BARD1, RAD51C, and RAD51D, which alter their function and/or their expression, have a significant association with breast cancer risk." (PMID 37372450, 2023). "Both BRCA1 and BARD1 are subject to post-translational modification, where the phosphorylation of various residues in each protein have been detected in breast cancer tissue and leukemia cells." (PMID 35327659, 2022). "Further, we assessed different aspects of the BARD1 gene including its expression profile in cancers, mainly breast cancer, prognostic survival value, and patients’ outcome, and critical interaction with other proteins." (PMID 35650591, 2022). "Nevertheless, truncating variants in BARD1, BRIP1, and RAD51C are associated with a moderate risk of female BC, generally accounting for less than 1% of Breast Cancers." (PMID 35053526, 2022). "Recently, three BARD1 inherited missense mutations were identified in the RING domain (Cys53Trp, Cys71Tyr, and Cys83Arg) in a family affected by breast cancer." (PMID 35650591, 2022). "BOADICEA was extended to further incorporate the associations of pathogenic variants in BARD1, RAD51C and RAD51D with breast cancer risk." (PMID 36162851, 2022). "Currently, science has determined the anti-breast cancer role of BARD1 in the BRCA1- dependent pathway." (PMID 35650591, 2022). "Recently, the BRCA1-associated ring domain (BARD1), that partners BRCA1 in DNA repair, has been confirmed as a moderate-risk breast cancer susceptibility gene." (PMID 35595798, 2022). "BRCA1, a RING-containing tumor suppressor E3 ligase and implicated in breast cancers, forms a heterodimeric RING complex with BARD1 in the nucleus of cells." (PMID 35327659, 2022). "Several reports also demonstrated the existence of other genes at medium and low penetrance (e.g., BRIP1, RAD51C, RAD51D, BARD1, and PALB2), which have been associated with both Breast Cancer (BC) and OC risk." (PMID 35053526, 2022). "The C-terminal of BARD1 Cys557Ser was assessed and showed a significant increase in breast cancer probability (P = 0.04, OR = 3.4 [95% CI 1.2–10.2])." (PMID 35650591, 2022).
breast cancer (continued). "The BRCA1-associated ring domain 1 (BARD1) protein is a binding partner of BRCA1 and is essential for DNA damage repair, which is reported to be associated with breast cancer susceptibility." (PMID 33933153, 2021). "Each BCSG was associated with at least three diseases except BARD1 and RECQL, which were only associated with breast cancer." (PMID 33959510, 2021). "ATM, BARD1, CHEK2, and RAD51D were associated with a moderate risk of breast cancer with ORs ranging from 2-fold to 4-fold." (PMID 34606182, 2021). "These clinical characteristics also suggested that BARD1 and RAD51D were breast cancer susceptibility genes in Chinese women." (PMID 34606182, 2021). "Among these, BRCA1, BRCA2, and PALB2 were still classified as high risk, and ATM, BARD1, CHEK2, and RAD51D were still classified as moderate risk breast cancer susceptibility genes in Chinese women." (PMID 34606182, 2021). "This study classified ATM, BARD1, CHEK2, and RAD51D as moderate risk breast cancer susceptibility genes in Chinese women." (PMID 34606182, 2021). "BARD1 is vital in the rapid relocation of BRCA1 to DNA damage sites and has been associated with increased risk of breast cancer in postmenopausal Japanese women." (PMID 32075053, 2020). "The BARD1 protein structure is like that of the BRCA1, however it is different from that of the BRCA2 (BReast CAncer type 2), the second gene associated with breast cancer." (PMID 33114377, 2020). "Analyzing structure and functions of the BARD1 gene, we believe that BARD1 gene can play an important role in the pathogenesis of breast cancer and in the mechanisms of chemo-resistance of cancer cells as well." (PMID 33114377, 2020). "Future clinical studies using longitudinal CT‐imaging analysis of adipose tissue and muscle mass in BRCA1/BARD1‐mutant breast cancer patients are awaited to provide this key information." (PMID 32730698, 2020). "We examined the correlation between nuclear FL BARD1 and p50 in a series of breast cancer specimens." (PMID 33024116, 2020). "Tamoxifen-resistant breast cancer cells highly overexpress BARD1 and BRCA1, resulting in chemoresistance to DNA-damaging therapies including cisplatin and doxorubicin, but not to paclitaxel." (PMID 32528278, 2020). "Further, tamoxifen-resistant breast cancer cells express observably more BARD1 and BRCA1, lending chemoresistance to DNA-damaging therapy especially in ER-positive breast cancer patients." (PMID 32528278, 2020). "A strong positive correlation between nuclear BARD1 and p50 protein was seen in both neuroblastoma and breast cancer specimens." (PMID 33024116, 2020).
breast cancer (continued). "BARD1, PALB2, and RAD51B variants have been identified in breast cancer families, whereas truncating RAD51C and RAD51D variants are mainly found in families with ovarian cancer or breast and ovarian cancer." (PMID 30689231, 2019). "The BARD1 protein, which heterodimerizes with BRCA1, is encoded by a known breast cancer susceptibility gene." (PMID 30925164, 2019). "Studies on TN breast cancer patients showed associations of breast cancer with mutations in moderate penetrance breast cancer susceptibility genes FALB2, BARD1, BRIP1, RAD51C, and RAD51D." (PMID 30249004, 2018). "Here, we report that tamoxifen-resistant breast cancer cells express significantly more BARD1 and BRCA1, leading to resistance to DNA-damaging chemotherapy including cisplatin and adriamycin, but not to paclitaxel." (PMID 29686231, 2018). "More importantly, high expression of BARD1 and BRCA1 was associated with poor prognosis of ER+ breast cancer patients, especially in those received radiation therapy." (PMID 29686231, 2018). "An additional 5.1% (95% CI: 2.4–8.5) are estimated to carry a pathogenic allele of a moderate-risk breast cancer susceptibility gene (i.e., ATM, BARD1, CHEK2, or NBN) bringing the total proportion of estimated carriers to 10.4% (95% CI: 6.5–14.9)." (PMID 29945567, 2018). "It is now apparent that mutations of several other genes, such as BARD1, PALB2 (Partner And Localizer Of BRCA2) and BRIP1 (BRCA1 Interacting Protein C-Terminal Helicase 1), contribute to familial breast cancer." (PMID 29292755, 2017). "In support of this notion, we found that both RAD51 and BARD1, a component of the BRCA1 breast cancer susceptibility HDR protein complex, readily accumulate at telomeres in Rap1−/− MEFs expressing TRF2ΔB and in WT MEFs expressing TRF2ΔB; L286R." (PMID 26941064, 2016). "PIK3R1 and PLCG1 are involved in intracellular signaling cascades and their differential regulation is known to be involved in tumorigenesis, while POU2F1 interacts with several known breast cancer-associated proteins (i.e. BRCA1, BARD1 and PARP1)." (PMID 17280605, 2007). "Thus, some of these novel polymorphisms may actually represent low penetrance modifiers of ovarian cancer risk, in a similar manner to BARD1 polymorphisms that were subsequently shown to be associated with increased breast cancer risk in the general population." (PMID 15918899, 2005).
breast cancer (continued). "At the molecular and protein levels, BARD1 shows a significant degree of structural and functional similarity to BRCA1, and breast cancers occurring in individuals with BARD1 germline PVs exhibit a similar somatic gene expression profile to those with BRCA1 pathogenic variants." (PMID 40805222, 2025). "However, BARD1 PVs have been identified in patients with not only breast cancer but also in patients with neuroblastoma, colon cancer, liver cancer, lung cancer, and acute myeloid leukemia." (PMID 40805222, 2025). "Deficiencies in the DNA damage repair pathway related genes constitute an important factor in the development of breast cancer, with approximately 10% of breast cancer cases being caused by mutations in HR genes, such as BRCA1, BRCA2, PALB2, BRIP1, BARD1, and RAD51C." (PMID 40830526, 2025). "This approach is particularly valuable when counseling individuals with variants in moderate-penetrance breast cancer genes like CHEK2, ATM, RAD51C, RAD51D, and BARD1, since the relative effect of risk factors is expected to be higher than in individuals with high-penetrance PVs." (PMID 40805171, 2025). "It is also noteworthy that the low frequency of BARD1 PVs (less than 1%) in HBOC patients contrasts sharply with the much higher frequencies of BRCA1 and BRCA2 PVs, reinforcing the view of BARD1 as a gene conferring a moderate to low risk for breast cancer." (PMID 41301857, 2025). "BARD1 and BRCA1/2 mutation carriers had a strong family history of breast cancer." (PMID 40805222, 2025). "In addition, it was also found that TCDD induced the expression of circRNA-BARD1 (circ_0001098), which inhibited breast cancer tumorigenesis via miR-3942-3p/BARD1 axis." (PMID 37241719, 2023). "Other genes with moderate, low, or uncertain penetrance that have been implicated in breast cancer, RECQL, RAD51B, ERCC3, MRE11A, RAD51D, BARD1, and NBN, had a yield of 0.3% (n = 7), 0.3% (n = 7), 0.3% (n = 6), 0.3% (n = 6), 0.2% (n = 4), 0.2% (n = 4), and 0.1% (n = 3), respectively." (PMID 35971132, 2022). "In this population, the frequency of the BARD1 Cys557Ser variant was not significantly different in case-control cases (P0.3) and is not correlated with elevated breast cancer risk." (PMID 35650591, 2022). "We next determined the power of the competing RVAS tests to identify the 8 breast cancer risk genes (BRCA1-Missense, BRCA1-LoF, BRCA2-Missense, BRCA2-LoF, PALB2, BRIP1, CHEK2 and BARD1) at the three TIER levels 5%, 0.1% and 0.01% and at three levels of VE of 2%, 1% and 0.5% (Iberian: S6 Fig)." (PMID 33606672, 2021). "BARD1 (OR: 3.1, 95% CI: 1.3–7.2); CHEK2 (OR: 2.5, 95% CI:1.4–4.6); RAD51D (OR: 2.2, 95% CI: 1.3–3.8); and ATM (OR: 2.1, 95% CI: 1.2–3.6) were classified as moderate risk breast cancer risk genes." (PMID 34606182, 2021). "Also, endogenous association of p50 and BARD1 was demonstrated in several cell lines, including primary mouse embryonic fibroblasts (MEFs), HeLa cells and MCF-7 breast cancer cells." (PMID 33024116, 2020). "Therefore, our newly characterized Bard1‐deficient, orthotopic metastasis model can be used to accelerate the evaluation of PARP inhibitor efficacy in metastatic breast cancers harboring sensitizing BRCA1/2 pathway mutations." (PMID 32730698, 2020). "Most of the relevant studies suggest the role of BARD1 in breast cancer is in TNBC patients." (PMID 33114377, 2020). "BRCA1 and BRCA2 germline pathogenic variants were found in 7.3% of the IBC patients, 6.3% had a mutation in other cancer genes (PALB2, CHEK2, ATM and BARD1), and 1.6% had a germline pathogenic variant in other genes not related with breast cancer." (PMID 32075053, 2020).
breast cancer (continued). "Similarly to other genes such as BARD1, RAD51D, BRIP1, and RAD51C, FANCM is emerging as a breast cancer predisposing factor conferring a greater risk specifically for these breast cancer subtypes." (PMID 31991861, 2020). "To further examine the role of BARD1, we obtained Bard1-null mouse mammary carcinoma cells." (PMID 33024116, 2020). "Recent studies have begun to demonstrate the utility of RNA-seq for identifying mRNA splicing events in breast cancer susceptibility genes, including BRCA1, BRCA2, PALB2, and BARD1." (PMID 31803232, 2019). "Increasing evidence suggests that BARD1 mutations is very likely to occur in patients with non-BRCA1/2 inherited breast cancer." (PMID 30975222, 2019). "Indeed, inactivation of BRCA1, BRCA2, PALB2, FAM175A, and BARD1 are synthetic lethal with PARG depletion in MCF7 breast cancer cells due to disruption of HR-mediated DDR." (PMID 30889383, 2019). "For the moderate-risk homologous recombination repair (HRR) breast cancer genes ATM, BARD1, CHEK2, and NBN, 3.3% (p = 7.2 × 10− 04) of unselected pancreatic cancer cases carried a clearly pathogenic variant, and weighted inclusion of HiP-VUS increased the proportion to 5.1% (p = 2.3 × 10− 08)." (PMID 29945567, 2018). "Higher BARD1 and BRCA1 expression is associated with worse prognosis of early breast cancer patients, especially the ones that received radiotherapy, indicating the potential use of PI3K inhibitors to reverse chemoresistance and radioresistance in ER-positive breast cancer patients." (PMID 29686231, 2018). "Degradation of BRCA1 is also mediated by the proteasome after HERC2 (HECT-type E3 ligase) targeting; BRCA1, together with its partner BARD1 (BRCA1-associated RING domain 1), have an important role in HR and loss of any of these proteins results in susceptibility to breast cancer." (PMID 28937603, 2017). "BARD1 might also be linked to TGF-β signaling, as upregulated BARD1 expression was shown along with TGF-β early response genes in breast cancer and was associated with endoglin upregulation, a co-receptor for TGF-β." (PMID 26415510, 2015). "Talazoparib, initially approved as a monotherapy in BRCA1/2-mutated breast cancer and in combination with enzalutamide for HR-deficient prostate cancer, is currently under Phase II investigation for patients with solid tumors harboring DDR gene mutations, including BARD1." (PMID 41009605, 2025). "However, the breast cancer risk estimates of BARD1 PVs for Caucasians and Asians show no substantial difference and the frequency of BARD1 mutations in general population controls (from mixed populations) is 0.09%." (PMID 40805222, 2025). "Therefore, a lack of NF2 ubiquitination in BRCA1- and BARD1-deficient breast cancer cells contributes to tumor formation." (PMID 39796693, 2024). "However, later studies found that three previously reported pathogenic variants are benign polymorphisms in the Australian population, indicating that BARD1 is not accurate enough to represent the high-penetrance susceptibility gene of breast cancer." (PMID 35185591, 2022). "Additionally, BARD1 was found to promote the ubiquitination of RNA polymerase II and prevent transcription of damaged DNA and ubiquitination of ER-alpha and beta that play a role in cellular proliferation during breast cancer development." (PMID 35650591, 2022). "In addition, the last V5 version of BOADICEA incorporates the effects of pathogenic variants (PVs), not only in BRCA1 and BRCA2 genes, but also in PALB2, CHEK2, ATM and BARD1 for the breast cancer model and RAD51D, RAD51C and BRIP1 for the ovarian cancer model." (PMID 35886069, 2022). "Thus, BARD1 mutations/ polymorphism was not suggested as a high penetrance susceptibility gene in familial breast cancer evolution among the Australian community." (PMID 35650591, 2022). "Mutations in the BARD1 gene confer a two- to three-fold elevated breast cancer risk, but it has not been determined whether or not they predispose to prostate cancer." (PMID 34771627, 2021).